ENSG00000249319 (novel protein)
Gene: Protein-coding gene on chromosome 7 (66,087,761 to 66,152,277, forward strand). Ensembl gene ENSG00000249319.
Genetic constraint (gnomAD): Loss-of-function variants: 34 observed, 39.1 expected, observed/expected ratio (o/e) 0.87, 90% interval 0.66 to 1.16. Missense variants: 290 observed, 356.84 expected, observed/expected ratio (o/e) 0.81, 90% interval 0.74 to 0.9. Synonymous variants: 124 observed, 139.38 expected, observed/expected ratio (o/e) 0.89, 90% interval 0.77 to 1.03.